MORC2 (MORC family CW-type zinc finger 2)
Description:
ATP-dependent chromatin remodeler essential for epigenetic silencing by the HUSH (human silencing hub) complex. Recruited by HUSH to target site in heterochromatin, the ATPase activity and homodimerization are critical for HUSH-mediated silencing. Represses germ cell-related genes and L1 retrotransposons in collaboration with SETDB1 and the HUSH complex, the silencing is dependent of repressive epigenetic modifications, such as H3K9me3 mark. Silencing events often occur within introns of transcriptionally active genes, and lead to the down-regulation of host gene expression. During DNA damage response, regulates chromatin remodeling through ATP hydrolysis. Upon DNA damage, is phosphorylated by PAK1, both colocalize to chromatin and induce H2AX expression. ATPase activity is required and dependent of phosphorylation by PAK1 and presence of DNA. Recruits histone deacetylases, such as HDAC4, to promoter regions, causing local histone H3 deacetylation and transcriptional repression of genes such as CA9. Exhibits a cytosolic function in lipogenesis, adipogenic differentiation, and lipid homeostasis by increasing the activity of ACLY, possibly preventing its dephosphorylation. Together with MPHOSPH8, mediates silencing of protocadherin genes in the nervous system (By similarity).
Synonyms: KIAA0852; ZCWCC1; ZCW3; AC004542.C22.1; CMT2Z; DIGFAN
Tractability: Small molecule: a structure with a bound ligand is known. PROTAC: UniProt records ubiquitination sites on it; ubiquitination databases record sites on it; its protein half-life has been measured.
Gene: Protein-coding gene on chromosome 22 (30,925,130 to 30,969,082, reverse strand). Ensembl gene ENSG00000133422.
Subcellular location: Nucleus; Cytoplasm, cytosol; Chromosome; Nucleus matrix
Subcellular location (Human Protein Atlas): Nucleoplasm; Cytosol
Pathways (Reactome):
Gene expression (Transcription): Regulation of endogenous retroelements by the Human Silencing Hub (HUSH) complex
Metabolism: Fatty acyl-CoA biosynthesis
Gene Ontology:
Molecular function: ATP binding; ATP hydrolysis activity; ATP-dependent chromatin remodeler activity; chromatin binding; magnesium ion binding; protein binding; protein homodimerization activity; zinc ion binding
Biological process: chromatin remodeling; constitutive heterochromatin formation; DNA damage response; transposable element silencing by heterochromatin formation
Cellular component: chromosome; cytoplasm; cytosol; heterochromatin; nuclear matrix; nucleoplasm; nucleus
Genetic constraint (gnomAD): Loss-of-function variants: 29 observed, 131.78 expected, observed/expected ratio (o/e) 0.22, 90% interval 0.16 to 0.3. The upper end of that interval is the gene's LOEUF score, 0.3, which puts it in group 1 of 6, group 1 being the genes least tolerant of losing a copy. Missense variants: 894 observed, 1,340.2 expected, observed/expected ratio (o/e) 0.67, 90% interval 0.63 to 0.7. Synonymous variants: 426 observed, 494.34 expected, observed/expected ratio (o/e) 0.86, 90% interval 0.8 to 0.93.
Gene-disease validity (ClinGen):
ClinGen rates the evidence that MORC2 causes each of these diseases.
Charcot-Marie-Tooth disease axonal type 2Z (autosomal dominant): Definitive. Any Charcot-Marie-Tooth disease in which the cause of the disease is a mutation in the MORC2 gene.
Leigh syndrome (autosomal dominant): Limited. A progressive neurological disease defined by specific neuropathological features associating brainstem and basal ganglia lesions.
Homologues: Orthologues: chimpanzee MORC2 (99% identical), macaque MORC2 (96% identical), dog MORC2 (95% identical), pig MORC2 (95% identical), guinea pig MORC2 (93% identical), rat Morc2 (92% identical), mouse Morc2a (91% identical), rabbit MORC2 (82% identical), rat Morc2b (76% identical), mouse Morc2b (74% identical), tropical clawed frog morc2 (67% identical), zebrafish morc2 (64% identical), and 1 more. Paralogues in human: MORC1 (35% identical).
Diseases named in the same sentence as MORC2 in open-access papers:
MORC2 is named in the same sentence as 61 diseases in open-access papers, as found by Europe PMC text mining. Sharing a sentence is not in itself a finding about the gene and the disease. The quoted sentences say what the papers report.
breast carcinoma (29 papers, 2011 to 2025). "While estradiol-induced MORC2 upregulation poses a potential risk in breast cancer, liver cancer has also been observed in Morc2a-deficient Morc2a p.S87L mice." (PMID 40760337, 2025). "Multiple studies have linked MORC family CW-type zinc finger 2 (MORC2) with DNA damage and resistance to radiotherapy and chemotherapy in breast cancer." (PMID 39285476, 2024). "This was the first study to describe MORC2’s role as a transcription activator in breast cancer cells in association with the transcription factor c-Myc." (PMID 37892209, 2023). "Mutations of MORC proteins are often observed in cancers, for example, the substitution mutation of MORC2 from methionine to isoleucine at residue 276 (M276I) promoted cell migration, invasion, and lung metastasis of breast cancer." (PMID 34839357, 2021). "Furthermore, increased MORC2 expression levels were linked to poor prognosis and unfavorable clinical outcomes in non-small cell lung and breast cancer." (PMID 37892209, 2023). "Notably, expression of a SUMOylation-deficient mutant MORC2 or administration of SUMO inhibitor enhances the sensitivity of breast cancer cells to DNA-damaging chemotherapeutic drugs." (PMID 36793866, 2023). "MORC2 mutations cause Charcot-Marie-Tooth neuropathy type 2Z disease, and recent research showed that MORC2 is aberrantly highly expressed in many cancers, including breast cancer, hepatocellular carcinoma cells, and gastric cancer cells." (PMID 36142569, 2022). "In addition to data stating the effects of mutations on breast cancer, accumulating evidence indicates that MORC2 expression is upregulated in breast cancer and MORC2 overexpression is related to unfavorable pathological characteristics and poor prognosis." (PMID 34839357, 2021). "A single nucleotide mutation in MORC1 was first detected in metastatic lobular breast cancer, indicating its potential role in the progression of breast cancer, and a mutation in MORC2 could induce the metastatic progression of triple-negative breast cancer." (PMID 34839357, 2021). "Inhibiting O‐GlcNAcylation markedly reduces the invasive ability of breast cancer cells, indicating that this modification drives tumor progression through MORC2‐mediated transcriptional mechanisms." (PMID 41394960, 2025). "Previous work in breast cancer cells has shown that estradiol inhibits lysosomal degradation of MORC2 through the GPER–PRKACA–chaperone-mediated autophagy pathway." (PMID 40760337, 2025). "For example, NAT10 promotes a mediator for DNA damage checkpoint activation, MORC2 K767Ac, and thus is considered a promising target for sensitizing breast cancer cells to DNA-damaging chemotherapy and radiotherapy." (PMID 39246323, 2024). "They concluded from these findings that MORC2 regulates β-catenin signaling to support breast cancer cell proliferation and migration." (PMID 37892209, 2023). "The effect of dynamic MORC2 SUMOylation on the sensitivity of breast cancer cells to chemotherapeutic drugs was examined through in vitro and in vivo functional assays." (PMID 36793866, 2023). "In breast cancer, it interacts directly with the CW‐ZF domain of MORC2, and PARylates MORC2 at the E516 and D517 residues." (PMID 36941223, 2023). "MORC2, a newly identified chromatin modifier, has been identified as a vital participator in some types of cancer, especially in breast cancer and liver cancer." (PMID 37737260, 2023). "E2- and ESR1-targeting drugs mediate breast cancer proliferation by preventing MORC2 lysosomal degradation via chaperon-mediated autophagy." (PMID 37892209, 2023). "They recognized that breast cancer patients with high-level expressions of MORC2, OGT, SNAIL, and CTGF had poor prognosis." (PMID 37892209, 2023). "Protein kinase cAMP-activated catalytic subunit alpha (PRKACA)-mediated phosphorylation of MORC2 on T582 abrogates CMA-mediated degradation of MORC2, leading to endocrine resistance of breast cancer cells." (PMID 36694209, 2023).
breast carcinoma (continued). "In response to DNA damage, the SUMOylation of MORC2 orchestrates chromatin remodeling and DNA repair and promotes chemoresistance in breast cancer." (PMID 37892209, 2023). "In conclusion, the findings presented here uncover a previously unrecognized functional and mechanistic role for MORC2 O-GlcNAcylation in breast cancer progression." (PMID 34974534, 2022). "Third, HSP90 N‐terminal inhibitor 17‐AAG effectively blocks MORC2‐mediated breast cancer progression, and this effect is independent on HSP90." (PMID 35522895, 2022). "In this study, we uncovered several interesting findings concerning the functional and mechanistic role of OGT-mediated MORC2 O-GlcNAcylation in breast cancer progression." (PMID 34974534, 2022). "Mutation of this site or pharmacological inhibition of OGT impairs MORC2-mediated breast cancer cell migration and invasion in vitro and lung colonization in vivo." (PMID 34974534, 2022). "In this study, we showed that mutation of MORC2 O-GlcNAcylation site (T556A) or pharmacological inhibition of OGT by OSMI-1 impairs MORC2-mediated breast cancer cell migration and invasion in vitro and lung colonization in a mouse xenograft mouse model." (PMID 34974534, 2022). "In recent years, studies from our lab have found that the chromatin-remodeling protein MORC2 acts as a crucial oncoprotein and promotes breast cancer metastasis." (PMID 36361605, 2022). "MORC2 has been documented to be overexpressed in 15 types of common human tumours including breast cancer." (PMID 35522895, 2022). "Collectively, these results suggest that MORC2 O-GlcNAcylation is critical for breast cancer progression, which can be blocked by OGT inhibitor OSMI-1." (PMID 34974534, 2022). "In support of these observations, knockdown of GFAT, SNAIL or CTGF compromises TGF-β1-induced, MORC2 O-GlcNAcylation-mediated breast cancer cell migration and invasion." (PMID 34974534, 2022). "OSMI-1, an OGT inhibitor, significantly suppresses MORC2-mediated breast cancer cell invasion and metastasis." (PMID 34974534, 2022). "In our study, we discovered that MORC2‐expressing breast cancer cells had greater sensitivity to 17‐AAG both in vitro and in vivo." (PMID 35522895, 2022). "Collectively, these findings uncover a previously unrecognized mechanistic role for MORC2 O-GlcNAcylation in breast cancer progression and provide evidence for targeting MORC2-dependent breast cancer through blocking its O-GlcNAcylation." (PMID 34974534, 2022). "The systematic work from our group recently shows that MORC2 is of importance in breast cancer progression." (PMID 35522895, 2022). "Together, 17‐AAG is effective against MORC2‐driven breast cancer progression in vitro and in vivo and this effect is related to MORC2 expression levels." (PMID 35522895, 2022). "Recent work from our group shows that MORC2 promotes breast cancer progression and resistance to endocrine therapy and DNA-damaging chemotherapy and radiotherapy." (PMID 34974534, 2022). "The stabilization of MORC2 is also related to breast cancer proliferation induced by estrogen and its analogs (such as 17β-estradiol) and resistance to antiestrogens (such as tamoxifen and fulvestrant) via a GPER1-PRKACA-CMA pathway." (PMID 34839357, 2021). "Results showed that high levels of MORC2 were associated with poor recurrence-free survival (RFS) and distant metastasis-free survival (DMFS) of breast cancer patients received chemotherapy." (PMID 31796101, 2019). "Our data revealed an essential role for endogenous CTNND1 in MORC2-enhanced migration and invasion of E-cadherin-deficient MDA-MB-231 and Hs578T breast cancer cells." (PMID 29228664, 2017). "Third, it identifies CTNND1 as a novel binding partner of MORC2, which is required for MORC2-mediated breast cancer migration and invasion." (PMID 29228664, 2017).
breast carcinoma (continued). "Here, we provide in vitro and in vivo evidence that MORC2 is dispensable for cell proliferation and cell-cycle progression, but promotes breast cancer invasion and metastasis in vitro and in vivo." (PMID 29228664, 2017). "We next investigated the molecular mechanism by which MORC2 promotes breast cancer invasion and metastasis." (PMID 29228664, 2017). "In this study, we addressed the functional and mechanistic roles for MORC2 in breast cancer development and progression." (PMID 29228664, 2017). "In summary, we provide the evidence for the first time that MORC2 promotes the migratory, invasive and metastatic potential of breast cancer, which depends, at least in part, on its PRD domain." (PMID 29228664, 2017). "Here, we show that MORC2 promoted breast cancer invasion and metastasis and these effects depended on a proline-rich domain (PRD) within its carboxy-terminal region spanning residues 601–734." (PMID 29228664, 2017). "Taken together, these results suggest that MORC2 promotes breast cancer invasion and metastasis through its PRD domain-mediated interaction with CTNND1." (PMID 29228664, 2017). "Second, it provides mechanistic insights into the metastasis-promoting activity of MORC2 in breast cancer depending, at least in part, on its PRD domain." (PMID 29228664, 2017). "Given that CTNND1 is implicated in the metastatic progression of breast cancer and that MORC2 interacts with CTNND1, we next assessed the role of CTNND1 in MORC2-enhanced migration and invasion of breast cancer cells." (PMID 29228664, 2017). "MORC2 (MORC family CW-type zinc finger 2) was over-expressed in breast cancer tissue and in situ carcinoma as compared to adjacent normal breast tissue." (PMID 22140552, 2011). "Consistently, MORC2 knockout sensitized breast cancer cells to PTX and VCR." (PMID 36967563, 2023). "Moreover, dynamically regulated SUMOylated MORC2 is important for chromatin remodeling and DNA repair in response to DNA damage and drives chemoresistance in breast cancer." (PMID 36793866, 2023). "Additionally, the knockdown of GFAT, SNAIL, or CTGF compromised the ability of TGF-β1-induced MORC2 O-GlcNAcylation-mediated breast cancer cell migration and invasion." (PMID 37892209, 2023). "In addition, recent work from our group demonstrated that MORC2 is involved in DNA damage response and contributes to the resistance of breast cancer cells to DNA‐damaging agents." (PMID 36967563, 2023). "To test whether MORC2 SUMOylation is important in resistance of breast cancer cells to ADR, we established xenograft tumor models with human LM2-4175 cells." (PMID 36793866, 2023). "Additionally, they demonstrated that the MORC2–c-Myc–LDHA signaling axis contributes to the migration of breast cancer cells." (PMID 37892209, 2023). "Moreover, treatment with OGT inhibitor OSMI-1 suppressed WT MORC2-mediated breast cancer cell migration and invasion." (PMID 34974534, 2022). "Furthermore, expression of an O-GlcNAcylation-defective MORC2 or knockdown of CTGF or SNAIL impairs TGF-β1-induced breast cancer cell migration and invasion." (PMID 34974534, 2022). "Moreover, O-GlcNAcylated MORC family CW-type zinc finger 2 (MORC2) at Thr556 is required for transcriptional activation of TGF-β1 to facilitate breast cancer cell migration and invasion." (PMID 35432358, 2022). "First, O-GlcNAcylation is a novel PTM of MORC2, which is required for breast cancer progression." (PMID 34974534, 2022). "Interestingly, it was recently shown that in breast cancer cells, estrogens upregulate MORC2 protein level by inhibiting MORC2 autophagic degradation." (PMID 35722617, 2022). "We recently demonstrated that MORC2 undergoes signaling-dependent phosphorylation, acetylation, and poly(ADP-ribosyl)ation, and these PTMs are implicated in the resistance of breast cancer cells to endocrine therapy drugs and DNA-damaging therapeutic agents." (PMID 34974534, 2022).
breast carcinoma (continued). "NAT10-mediated acetylation of MORC2 could force the cell to pass through the G2 checkpoint and confer resistance to DNA-damaging treatments in a breast cancer study." (PMID 34362389, 2021). "As MORC2 is predominately localized in the nuclear, we hypothesized that the involvement of MORC2-CTNND1 interaction in breast cancer progression is mainly mediated by nuclear CTNND1." (PMID 29228664, 2017). "First, it establishes MORC2 as a novel regulator of breast cancer invasion and metastasis." (PMID 29228664, 2017). "However, the mechanistic role for MORC2 in breast cancer development and progression remains unexplored." (PMID 29228664, 2017). "Notably, radiation has been shown to enhance NAT10-mediated acetylation of MORC2 in breast cancer, suggesting that NAT10 may serve as a potential therapeutic target to overcome RT resistance." (PMID 40109769, 2025). "Thus, whether there is a positive feedback loop between GFAT and TGF-β1 to induce MORC2 O-GlcNAcylation in breast cancer cells remains to be addressed in the future." (PMID 34974534, 2022). "To address whether MORC2 O-GlcNAcylation is involved in TGF-β1-mediated breast cancer cell migration and invasion, we reconstituted empty vector pMSCV or Flag-MORC2 (WT or T556A) into MORC2-KO LM2–4175 and BT549 cells by lentiviral infection and then treated with or without TGF-β1." (PMID 34974534, 2022). "In addition, we identified a gain-of-function mutation of MORC2 that was associated with cancer metastasis and that revealed a post-translational modification of MORC2, namely GlcNAcylation at threonine 556, which enhances breast cancer cell migration and invasion." (PMID 36361605, 2022). "Therefore, targeting O-GlcNAc signaling may be a potential therapeutic approach for MORC2-mediated breast cancer progression." (PMID 34974534, 2022). "In addition, MORC2 expression was shown to be upregulated following endocrine therapy in breast cancer, contributing to its resistance to treatment, and MORC2 could regulate the resistance to chemotherapy and radiotherapy." (PMID 34839357, 2021). "Interestingly, two recent gene expression profiling studies revealed that the expression levels of MORC2 are up-regulated in breast cancer tissues as compared with adjacent normal breast tissues and are associated with recurrence risk of patients with highly aggressive triple-negative breast cancer." (PMID 29228664, 2017). "MORC family CW-type zinc finger 2 (MORC2) is a newly identified chromatin remodeling protein with emerging roles in the regulation of DNA damage response and gene transcription, but its mechanistic role in breast cancer development and progression remains unexplored." (PMID 29228664, 2017). "For example, the Thr556 residue of the chromatin remodeler MORC2 can be O‐GlcNAcylated, and modified MORC2 promotes the expression of TGF‐β1 downstream target genes CTGF and SNAIL, both of which are critical for breast cancer invasion and metastasis." (PMID 41394960, 2025). "The acetylation of MORC2 by NAT10 regulates cell-cycle check point control and resistance to DNA-damaging chemotherapy and radiotherapy in breast cancer." (PMID 37892209, 2023). "In the present study, we found that dynamic SUMOylation of MORC2 by TRIM28 orchestrates chromatin remodeling and DNA repair in response to DNA damage and drives chemoresistance in breast cancer." (PMID 36793866, 2023). "In order to understand the internal regulatory mechanism of MORC2, we carried out CHX chase assays to determine its turnover rate in six commonly used cell lines of three distinguishing breast cancer molecular subtypes." (PMID 35522895, 2022). "Collectively, we discovered that HSP90 N‐terminal inhibitors disrupt the homodimer formation of oncogenic ATPase MORC2 to induce its autophagic degradation in a HSP90‐independent manner, and consequently, suppress MORC2‐driven breast cancer progression." (PMID 35522895, 2022).